MDM2 (MDM2 proto-oncogene)
Diseases named in the same sentence as MDM2 in open-access papers (continued):
Sharing a sentence is not in itself a finding about the gene and the disease.
tumor (continued). "Here we present in silico, in vitro, and mouse xenograft studies that suggest that specifically targeting HDAC2 reduces MDM2 expression and has anti-tumor affects in DDLPS." (PMID 31620242, 2019). "We detected that Bmal1 has a direct link with tumor invasion in the brain through interaction with Mdm2 and other cancer-related genes." (PMID 31523185, 2019). "The knockdown of MDM2 in ERα+ T47D orthotopic tumors decreased primary tumor volumes, supporting our previous finding that estrogen-activated MDM2 increases cell proliferation." (PMID 30642351, 2019). "Recent study has identified a predictive gene signature, which determines sensitivity to MDM2 inhibition by DS-3032b, and validated it in patient-derived tumor xenograft (PDX) models and ex vivo in human AML cells." (PMID 31310659, 2019). "MDM2 amplification and overexpression are involved in chemotherapy and radiotherapy resistance in tumor cells via clearly mechanisms." (PMID 31440117, 2019). "A recent series of studies, including ours, indicate that MDM2 is able to interact with other cellular molecules involved in tumor promotion and metastasis, such as XIAP, VEGF, and Akt." (PMID 31428819, 2019). "The combination treatment of the VEGF inhibitor, bevacizumab, and the MDM2 inhibitor, nutlin-3, significantly inhibits tumor proliferation and angiogenesis." (PMID 31440117, 2019).
tumor (continued). "The HDM201 compound developed by Novartis is an imidazopyrrolidinone scaffold-based inhibitor of MDM2 which showed a significant anti-tumor activity in vitro and more efficient and better pharmacokinetic and pharmacodynamic profiles in in vivo models." (PMID 31527430, 2019). "We found that depletion of MDM2 resulted in a non–statistically significant reduction in the average primary tumor volume at all points during the experiment." (PMID 30642351, 2019). "MDM2 overexpression has been found in both malignant tumor cells and patients with primary resistance to EGFR inhibitors." (PMID 31440117, 2019). "In fact, p53EE was even constitutively stabilized in various tumor types arising in p53EE/EE mice, indicating escape from Mdm2‐mediated degradation." (PMID 31483066, 2019). "Advanced cancer patients with MDM2 overexpression developed tumor progression or even hyperprogressive disease after PD-1 inhibitor treatment." (PMID 31440117, 2019). "Along the same lines, another study found that p73 deletion augmented the effects of MDM2 overexpression in the development of B-cell lymphomagenesis in mice, which was shown to promote genomic instability and tumor development." (PMID 31905981, 2019).
tumor (continued). "Immunohistochemical analysis recapitulated the observations in cells, confirming an increased expression of both MDM2 and p21 in the R248W tumours compared to R175H." (PMID 30524726, 2018). "The downregulation of MDM2 following treatment with CDK4/6 inhibitors also induces many cultured tumor cell lines derived from different types of malignancies to progress from quiescence into senescence." (PMID 29789718, 2018). "Our previous studies have shown that MDM2 up-regulation triggers tumor angiogenesis and thereby increases the metastatic ability through modulation of various pro-angiogenic pathways." (PMID 29748481, 2018). "This study suggests that a small subset of most tumor types have MDM2 amplification as well as pharmacologically tractable co-alterations." (PMID 30148248, 2018). "We have previously observed in tumour cells that MDMX protein levels are reduced by suppression of a range of splicing factors but that MDM2 mRNA splicing is selectively sensitive to knockdown of SF3B1." (PMID 29796170, 2018). "The reported incidence of MDM2 amplification in various series conducted in single tumor types (0% to 6.3%) is consistent with our findings." (PMID 30237864, 2018).
tumor (continued). "Then, we conclude that Mdm2 is good for enhancing DNA‐damage response, and hence considered as a tumour suppressor." (PMID 29337287, 2018). "Our experiments were designed to explore the impact of MDM2 overexpression, specifically on the levels of angiogenesis-related genes, which can also play a major role in tumor propagation and increase its metastatic potential." (PMID 29748481, 2018). "Another group has recently shown that a combination of ceritinib, an ALK inhibitor, and CGM097, a MDM2 inhibitor, showed increased anti-tumour activity, and attenuated resistance to the ALK inhibitor in ALK-mutated NB cells." (PMID 29760954, 2018). "Being aware that MDM2 amplification is not restricted to DDLS39, our approach in this study was to prioritize clinical and histological findings over MDM2 status for tumor classification." (PMID 30018380, 2018). "MDM2 as one of E3 Ub-protein ligases is able to bind to p73 at the N-terminal region and inhibits tumor angiogenesis by promoting HIF-1α degradation." (PMID 29362483, 2018). "Because MDM2 amplification was analyzed in multiple tumor types, the number of cases with MDM2 amplification per tumor type is small for any meaningful analysis of correlations." (PMID 30237864, 2018). "In a small pilot study using seven pre- and post-treatment paired tumor sample biopsies from WD/DDLS patients who received palbociclib on clinical trial we had shown that the level of MDM2 was reduced in those who had a longer PFS." (PMID 29789718, 2018).
tumor (continued). "Certain studies also reveal that PRDM5 expression downregulate several oncogenes like CDK4, TWIST1, and MDM2 thereby preventing tumour progression." (PMID 28144288, 2017). "Our data predicted that the estradiol stimulate tumor apoptosis by elevating the level of hnRNPA1, and then influenced MDM2 expression in different types of cell lines." (PMID 28035066, 2017). "There are a number of therapeutic strategies that block the function of MDM2 and promote tumor cell death." (PMID 29065514, 2017). "Consistent with the experiment in vitro, estradiol reduced MDM2 expression through elevating the level of hnRNPA1 in A375 tumor tissue." (PMID 28035066, 2017). "Tumorigenic functions of overexpressed Mdm2 facilitate tumor metastasis and progressive forms of the disease in many human tumors including osteosarcomas, breast, prostate, and colon cancers." (PMID 28218667, 2017). "In 1996, multiple-sized MDM2 transcripts were identified from tumor samples in the lab of Lunec and named from MDM2a to MDM2e." (PMID 28035066, 2017). "For instance, amplifications in 8q21 have been associated with high tumour grade, high levels of Ki67 and other proliferation markers, including MYC, MDM2 and CCND1." (PMID 28351365, 2017). "Many studied found that RBM38 exhibited its tumor growth inhibiting activity by stabilization of p21, p73 and HuR transcripts or destabilization of MDM2 and c-Myc transcripts, via binding to AREs in the 3′-UTR of their mRNAs." (PMID 29052531, 2017). "Using high resolution confocal microscopy, we evidenced phagocytosis of tumor cells by MDM2 characterized by the uptake of tumor cells by macrophages and the establishment of larges vacuoles referred to as phagosomes." (PMID 29245952, 2017).